TNF (tumor necrosis factor)
Diseases named in the same sentence as TNF in open-access papers (continued):
Sharing a sentence is not in itself a finding about the gene and the disease.
tumor (continued). "Recent preclinical studies have expanded the therapeutic landscape by demonstrating that targeting TNF-α or its downstream pathways such as STAT3 and CSF-1 can significantly reduce tumor growth and metastatic potential." (PMID 40558596, 2025). "According to certain studies, TNF-α and TGF-β were reported to induce the expression of VEGF in HCC, which can promote angiogenesis, tumor growth, and metastases." (PMID 40406417, 2025). "NKT-like CD4-CD8+ cells interact with tumor cells by releasing cytolytic proteins and producing of a wide range of cytokines, such as IFN-γ and TNF-α, affecting other immunocompetent cells, including DCs, T lymphocytes, and NK cells." (PMID 41156469, 2025). "In contrast, lymphocytes have antitumor activity, suppressing tumor growth and metastasis through the secretion of interferon-γ (IFN-γ) and tumor necrosis factor-α (TNF-α)." (PMID 40506880, 2025). "Tumor necrosis factor-α (TNF-α) serves as an additional upstream regulator; the RGD (Arg-Gly-Asp)-toxin peptide has been reported to inhibit TNF-α-induced MMP-9 secretion, resulting in suppressed tumor-cell proliferation." (PMID 41181710, 2025). "Signaling pathways that play a key role in tumor progression, including MHC‐II, Laminin, and TNF, provide important instructions for tumor prevention and treatment." (PMID 40062730, 2025). "GSDMB expression, induced by tumor-infiltrating CD8+ T lymphocytes and immune cell-released cytokines like TNF-α and IFN-γ, establishes a positive feedback loop." (PMID 41291696, 2025). "Given that TNF-α blockade is central to AS management, understanding the dual role of TNF-α in tumor biology provides important context for interpreting these findings." (PMID 41302997, 2025). "Immune cells in the TME, including macrophages, neutrophils, and dendritic cells, are recruited by tumor-released chemoattractants and cytokines such as VEGF, tumor necrosis factor-alpha (TNF-α), and angiopoietin-2." (PMID 40647432, 2025). "For example, DC-secreted TNFα can promote RIPK-dependent apoptosis in tumor cells, which allows for sampling of tumor antigen by DCs and further induction of anti-tumor immunity." (PMID 40663561, 2025). "Accordingly, these cells produce high levels of pro-inflammatory cytokines, such as TNF, IL-1β, IL-6, IL-12, IL-23, and CCL2, to promote immune responses against bacteria, intracellular pathogens, and tumor cells." (PMID 40109347, 2025). "Numerous studies have reported significant associations between the expression levels of inflammatory cytokines—including IL-6, CXCL9, TNF-α, IL-17A, and IL-32—and LUAD tumor stage, metastasis, and prognosis." (PMID 40136462, 2025). "Our previous studies demonstrated a significant increase in TNF-α, IL-6, IL-18, IL-1β, and INF-γ in the skeletal muscle of tumor-bearing animals, which normalized after treatment with withaferin A (WFA)." (PMID 39996717, 2025). "As a result, there was an increase in both the number and percentage of tumor-infiltrating CD8+ T cells, as well as elevated levels of IFN-γ+ and TNF-α+ CD8+ T cells in shZdhhc3 tumors compared to control shRNAs." (PMID 40341398, 2025). "In this analysis, we found that cytotoxic CD4+ T cells largely correlated with reduced tumor growth in the triple therapy group, with the smallest tumors having the highest frequencies of CD4+ T cells with higher IFNγ and TNFα expression." (PMID 41171165, 2025). "For instance, CD3+ T-cell density was inversely correlated with the abundance of F. nucleatum, which stimulated tumor-promoting cytokines including IL-17 and TNF-α (tumor necrosis factor-α) through NF-κB signaling." (PMID 40941154, 2025). "Among various cytokines, TNF-α and TGF-β are essential in playing different functions at various stages of tumor development." (PMID 40294146, 2025).
tumor (continued). "These cells exert their anti-tumor effects by secreting cytotoxic molecules and cytokines, including perforin, granzymes, interferon-γ (IFN-γ), and tumor necrosis factor-α (TNF-α)." (PMID 41341383, 2025). "Immunohistochemical analysis was performed in all cases to assess the expression of TNF-α and IFN-γ as indicators of functional immune activity within the tumor microenvironment." (PMID 41150769, 2025). "Pre-clinical data show that PD-1 blockade (nivolumab) enhanced CAR-iNKT proliferation, cytokine production (IL-2, TNF-α, IFN-γ, and granzyme B) and effectively reversed CAR-iNKT exhaustion upon tumor rechallenge, translating into deeper tumor control." (PMID 40718496, 2025). "When PD-L1 on tumor cells binds to PD-1 on T cells, this interaction suppresses T cell proliferation, cytokine secretion (e.g., IFN-γ, TNF-α), and cytotoxic activity, ultimately leading to T cell dysfunction or exhaustion." (PMID 40539049, 2025). "NE promotes tumor cell proliferation by blocking tumor apoptosis mediated by tumor necrosis factor-α (TNF-α) and stimulates the release of vascular endothelial growth factor (VEGF) to promote tumor angiogenesis." (PMID 40282474, 2025). "CTLs eliminate cancer cells through two main mechanisms: direct perforin-dependent destruction and secretion of inflammatory cytokines, such as tumor necrosis factor (TNF) and interferon (IFN) alpha (INF-α), which increase tumor immune sensitivity." (PMID 40392714, 2025). "In macrophages, NPs modulate cytokines such as Tumor Necrosis Factor (TNF)-α, nitric oxide (NO), interleukin-(IL)−10 (IL-10), and IL-1beta (IL-1β) secretion in both tumor and non-tumor cells." (PMID 40643749, 2025). "Studies have shown that HuR promotes chronic inflammation by stabilizing TNF-α and IL-6 mRNAs and enhancing their expression within the tumor microenvironment (TME), thereby suppressing anti-tumor immune responses." (PMID 41200195, 2025). "Evaluation of macrophage activating cytokines showed that GB2 treatment indeed led to a significant upregulation of IL-6, TNF-α, and CXCL10 both in tumor and serum." (PMID 39744236, 2025). "Tumor necrosis factor-alpha (TNF-α), a pro-inflammatory cytokine secreted by both tumor and immune cells, similarly plays a crucial role in regulating multiple signaling pathways." (PMID 41267807, 2025). "This change is accompanied by an upregulation of pro-inflammatory cytokines such as interleukin-6 (IL-6) and tumor necrosis factor-alpha (TNF-α), further enhancing the anti-tumor immune response." (PMID 40330466, 2025). "TNF-α and IFN-γ play roles in tumor cell killing and contribute to T cell-induced bystander tumor cell lysis by upregulating ICAM-1 and Fas." (PMID 39806405, 2025). "Intrinsic to the success of CAR therapy is the activation of the immune system via cytokines such as IL-1, IL-6, IL-10, TNF-a, and interferon (IFN)-g to kill tumor cells." (PMID 40264764, 2025). "The KEGG pathway analysis revealed that the upregulated genes in Scissor+ epithelial cells were enriched in pathways related to focal adhesion, tight junctions, TNF signaling, and ECM-receptor interactions, which are characteristic of tumor metastasis." (PMID 41050411, 2025). "In a previous study, CANX was found to promote T cell activation and IFN-γ and TNF-α secretion by positively regulating MHC-1, thus enhancing the T cell killing effect on mouse tumor cells and immunocyte infiltration." (PMID 40787468, 2025). "This dual activation enhances the immunostimulatory milieu, as seen in reduced tumor proliferation (via Ki67 staining) and increased cytokine production (e.g., CCL5, CXCL10, TNFα) in syngeneic models." (PMID 41029427, 2025). "The tumor microenvironment also showed decreased production of pro-tumorigenic factors like VEGF, arginase, and TNF-α." (PMID 41300283, 2025).
tumor (continued). "Compared to the blank group, the high-fat diet-fed model group exhibited increased interleukin (IL)-6 and tumor necrosis factor (TNF)-α levels, showing enhanced inflammation and tumor development." (PMID 40869014, 2025). "Omega-3s reduce the synthesis of pro-inflammatory cytokines such as TNF-α and IL-6, and suppressive factors like prostaglandin E2 (PGE2), which inhibit T-cell function in the tumor microenvironment." (PMID 40141831, 2025). "Resveratrol has been shown to downregulate the production of pro-inflammatory cytokines, such as TNF-α, IL-6, and IL-1β, thereby disrupting the signals promoting inflammation within the TIME and hindering tumor growth and progression." (PMID 40940890, 2025). "Sustained pro-inflammatory cytokine production (notably IL-6, TNF-α, and IL-2R) induces CD4+ T-cell exhaustion and accelerates tumor progression." (PMID 40969752, 2025). "Therapeutic activation of neutrophils by TNF-α, CD40 agonist, and tumor-binding antibody contributes to massive ROS production and tumor eradication independently of T cells." (PMID 40050933, 2025). "Tumor cells release cytokines like IL‐6, CRP, and TNF‐α, as well as chemokines, angiogenic factors, and growth factors, inducing inflammatory responses that can promote or inhibit tumor growth." (PMID 40387308, 2025). "There was little or no STAT1 expression even after IFN treatment in some tumor cells and tumor-derived cell lines, and STAT1-depleted cells resisted apoptosis in response to TNF or IFN-gamma." (PMID 40241721, 2025). "PERK inhibition in MDSCs led to reduced immunosuppressive activity along with increased expressions of anti-tumor cytokines including IL-12 and TNF-α and enhanced CD8+ cell-mediated anti-tumor immunity." (PMID 40725182, 2025). "Tumor microenvironment analysis revealed remodeling of the myeloid compartment, significant induction of IFN-γ, TNF-α, and CXCL9 and broad gene expression reprograming." (PMID 40280970, 2025). "A central molecular mechanism involves the suppression of the NF-κB signaling pathway, leading to reduced expression of TNF-α and IL-6, thereby lowering inflammation in the TME and inhibiting tumor growth and metastasis." (PMID 41480347, 2025). "In summary, our results showed no indication for Fusobacterium-mediated M2 polarization of macrophages in the CRC tumor samples but, in contrast, a pro-inflammatory TME driven by inflammatory cytokines such as CXCL8, IL-6, and TNF-α." (PMID 40895532, 2025). "Additionally, fullerene nanomaterials have been demonstrated to mitigate TNF-α secretion by scavenging excessive ROS or modulating redox homeostasis, thereby suppressing the activation of inflammation-associated signaling pathways such as NF-κB and MAPK/ERK in tumor microenvironment." (PMID 40537773, 2025). "Here we show that Tregs contain two subpopulations, respectively committed to TNF production and to TNFR2‐mediated TNF sensing, which both increase at the tumor site." (PMID 40977146, 2025). "However, at high concentrations, TNF-α may directly induce tumor cell death." (PMID 40563367, 2025). "The increase in granzyme B, one of the key molecules in cell killing action, and TNF and IFN-γ, which are potent immune activators, implies that the efficacy of T cells against tumor cells is significantly enhanced." (PMID 39941980, 2025). "TNF‐α, EMT induction, and inflammatory responses are highly correlated with promoting the invasiveness and metastatic potential of tumor cells as well as modifying the tumor immune microenvironment." (PMID 40226936, 2025). "NeoAg-specific CD4+ T cells can also secrete inflammatory cytokines such as IFN-γ and TNF within the tumor microenvironment (TME), which can directly inhibit tumor growth, suppress pro-tumor accessory cells, and inhibit tumor vasculature." (PMID 40196575, 2025).
tumor (continued). "The results demonstrated significantly higher mRNA expression of IFN-γ, TNF-α, IL-2, IL-12a, CXCL9, and CXCL10 in the tumor tissue of the PD-L1-KO/ZG16 overexpression group compared to the control group." (PMID 39958358, 2025). "TNF-α and IFN-γ enhance GSDMB expression, sensitizing tumor cells to killer lymphocyte–mediated cytotoxicity, while IRF2 transcriptionally upregulates GSDMD for pyroptosis." (PMID 40200299, 2025). "It targets IRF3 and inhibits TNF‐α signaling through NF‐κB, IFN‐α, and IFN‐γ pathways, facilitating immune escape of tumor cells." (PMID 39712454, 2025). "Next, we measured TNF-α and TWEAK levels in the perilymph and blood of patients with sporadic VS undergoing translabyrinthine craniotomy for tumor resection and observed a similar trend as in the mouse model of VS." (PMID 39923035, 2025). "Based on the multiplex immunoassay profiling, we observed that there were higher expressions of VEGF-A, MCP-1, MMP-1, TNF-α, and CD40L in the CSF samples of CPP patients in comparison to non-tumor patients." (PMID 40843692, 2025). "Flow cytometric analysis of tumor-infiltrating lymphocytes demonstrated enhanced CD8+ T cell activation and increased TNF-α and IFN-γ production in EGR3-overexpressing tumors." (PMID 41472745, 2025). "Compared with WT controls, the protein expression of MHC I, MHC II, TNF-α and IFN-γ were higher, while the expression of Arg-1 and iNOS were lower in Lnk–/– tumor MDSCs." (PMID 40796725, 2025). "ELISA analysis of tumor tissues revealed that B7 significantly enhanced IFN‐γ, TNF‐α, GzmB, and perforin levels (P < 0.05 vs vehicle), whereas CD155 overexpression diminished this immunostimulatory functionality of B7 (all P < 0.05 vs corresponding vehicle)." (PMID 40492418, 2025). "Th1 cells release anti-tumor cytokines like interleukin (IL)-2, interferon (IFN)-γ, and tumor necrosis factor (TNF)-α, while Th2 cells release immunosuppressive IL-4, IL-5, IL-10, and IL-13." (PMID 40260236, 2025). "The NF-κB signaling pathway activates proinflammatory signals (such as TNF) through IL17RE and CRP, thereby promoting tumor growth in an inflammatory environment." (PMID 40989695, 2025). "TNF-α and IFN-γ present in supernatants of TSLP-activated CD4+ T cells were required for PyMt tumor suppression." (PMID 40873585, 2025). "The dual roles of key cytokines such as TNF-α, TGF-β, IL-6, and IL-10, which act as both tumor suppressors and promoters depending on the tumor context, highlight the complexity of targeting these pathways therapeutically." (PMID 40933989, 2025). "CD8+ cytotoxic T cells are the most powerful tumor-killing immune cell, they act by releasing cytotoxic molecules IFN-γ, TNF-α and Gzms-B." (PMID 40804393, 2025). "CASP3 (Caspase-3) inhibits bacterial growth through the tumor necrosis factor (TNF) signaling pathway and other tumor-related cascades." (PMID 40822022, 2025). "Second-generation dexosome therapies have further enhanced anti-tumor effects by promoting NK cell function via NKp30 receptor engagement and BAG6 ligand expression, which together trigger TNF-α and IFN-γ secretion." (PMID 40573922, 2025). "The tumor necrosis factor (TNF) superfamily currently comprises 19 ligands and 29 receptors, some of which are expressed on immune cells and participate in the development of tumor-specific immune responses." (PMID 39218939, 2024). "Upon antigen stimulation, CD8+ T cells can rapidly differentiate into effector cells and produce a multitude of effector cytokines (e.g., IL-2, TNF-α, and IFN-γ) and granzyme B to effectively eliminate tumor cells." (PMID 39519411, 2024). "This is because downregulating levels of TNF-α and IFN-γ, which are involved in the inflammatory response, can potentially compromise the efficacy of tumor immunotherapy." (PMID 39456702, 2024). "Both SIA‐CIgG CAR‐T cells and HER2 CAR‐T cells secreted more IL‐2, IL‐5, TNF‐α, IFN‐γ, and IL‐13 compared to non‐transduced T cells when eliminating tumor cells." (PMID 39178136, 2024).
tumor (continued). "More importantly, the proportions of tumor‐infiltrating IFNγ+, GZMB+, and TNFα+ CD8+ T cells were significantly elevated after SRC‐1 deletion, indicating more effector CD8+ T cells were activated." (PMID 38953362, 2024). "In tumour tissues, the abundance of GzmB, perforin, TNF-α, and IFN-γ is significantly decreased in CD4+, CD8+ T cells, and NK cells compared to non-tumour tissues." (PMID 38893071, 2024). "For instance, elevations in tumor-secreted inflammatory cytokines such as interleukin (IL)-1β, IL-6, C-reactive protein (CRP), and tumor necrosis factor (TNF)-α trigger systemic inflammation and activation of skeletal muscle catabolic pathways." (PMID 40443828, 2024). "In addition to tumor cell killing, we measured the secretion of the pro-inflammatory cytokines IFN-γ, TNF-α and IL-2, which might be relevant on the one hand for potential side effects but also on the other hand for the anti-tumor response and the modulation of the TME." (PMID 38582787, 2024). "Herein, we revealed that ENTPD2 strongly suppressed the production of the cytokines IFN-γ, TNF-α, and Granzyme B by CD8+ T-cell subsets in MC38 tumor tissues." (PMID 38755598, 2024). "Total flavonoids from Prunella vulgaris increased the expression of TNF-α and IFN-γ in serum of tumor-bearing mice and improved anticancer and anti-inflammatory ability in SMMC-7721 cells." (PMID 39139212, 2024). "The killing of tumor cells by CD8+ T cells was more significant and more IFN-γ and TNF-α were produced after co-coculture." (PMID 38994031, 2024). "Th1 subtype CD4+ T cells contribute to anti-tumor activity by assisting cytotoxic CD8+ T cells and B cells and directly killing cancer cells through interferon and tumor necrosis factor-alpha production." (PMID 39926600, 2024). "Given the increase in pro-inflammatory CD4(+) T cells after oHSV treatment, we next analyzed IFN-γ, TNF-α, IL-4, IL-17A, and IL-21 intracellular expression within the CD4(+) tumor infiltrates." (PMID 38895115, 2024). "In all cases we observed that isolated tumor cells remained sensitive to LCL161 and TNF-α cotreatment in a dose-dependent fashion." (PMID 39147758, 2024). "One day after HIFU therapy, no significant changes were detected in tumor cytokine levels; however, by Day 3, elevated levels of tumor IFN‐γ, TNF‐α, and IL‐6 were observed in the T‐MBs + HIFU group compared to the control group." (PMID 39431644, 2024). "The functional characteristics of CD8+ T cells, particularly cytokine secretion (IL-2, TNF-α, IFN-γ) and cytolytic granule presence (granzyme B), are intricately tied to their anti-tumor activity." (PMID 39450177, 2024). "Positive T cell‐mediated responses were observed in TEFT‐treated tumor areas, as evidenced by CD45 activation and subsequent tumor necrosis factor (TNF)‐α production to induce cell death." (PMID 38715344, 2024). "While the mice model of HNSCC treated with radiotherapy, there showed an increase in the production of the chemotactic factor CCL2 in tumor cells, leading to the accumulation of CCR2-dependent TNF-α-producing monocytes/macrophages and CCR2+ Tregs." (PMID 38650924, 2024). "We detected a stronger pro-inflammatory environment in the lungs than in tumours of IAV-infected tumour-bearing mice, indicated by increased IFNγ, IL-12 and TNFα concentrations." (PMID 38271469, 2024). "CD56+ drives the maturation of NK cells and is weak in cytotoxicity but strong in the production of anti-tumour cytokines such as IFN-γ and TNF-α." (PMID 38973003, 2024). "The presence of IL-17 in the TME also leads to an increase in TNF-α, which recruits myeloid cells through TNF receptor 1 (TNFR1) proinflammatory cytokines, further promoting tumor development." (PMID 39906741, 2024). "In the early stages of tumorigenesis, multiple signals in the TME, such as IL-6, TNF-α, and chemotactic protein-2 (CCL2), prompt monocytes to migrate to tumor tissues, where they differentiate into TAMs." (PMID 39697553, 2024).